PANK2 (pantothenate kinase 2)
Description:
[Isoform 1]: Mitochondrial isoform that catalyzes the phosphorylation of pantothenate to generate 4'-phosphopantothenate in the first and rate-determining step of coenzyme A (CoA) synthesis. Required for angiogenic activity of umbilical vein of endothelial cells (HUVEC). [Isoform 4]: Cytoplasmic isoform that catalyzes the phosphorylation of pantothenate to generate 4'-phosphopantothenate in the first and rate-determining step of coenzyme A (CoA) synthesis.
Synonyms: C20orf48; HSS; FLJ11729; PKAN; HARP; NBIA1
Tractability: Small molecule: a structure with a bound ligand is known. PROTAC: ubiquitination databases record sites on it; its protein half-life has been measured; a small molecule that binds it is known.
Target class: Enzyme
Chemical probes: PZ2891 (high quality)
Gene: Protein-coding gene on chromosome 20 (3,888,839 to 3,929,887, forward strand). Ensembl gene ENSG00000125779.
Subcellular location: Mitochondrion (Isoform 1); Mitochondrion intermembrane space; Nucleus; Cytoplasm (Isoform 2); Cytoplasm (Isoform 3); Cytoplasm (Isoform 4)
Subcellular location (Human Protein Atlas): Cytosol
Pathways (Reactome):
Metabolism: Coenzyme A biosynthesis
Gene Ontology:
Molecular function: pantothenate kinase activity; protein binding; ATP binding
Biological process: angiogenesis; coenzyme A biosynthetic process; pantothenate metabolic process; regulation of fatty acid metabolic process; regulation of triglyceride metabolic process
Cellular component: cytoplasm; cytosol; mitochondrial intermembrane space; mitochondrion; nucleus
Genetic constraint (gnomAD): Loss-of-function variants: 36 observed, 42.63 expected, observed/expected ratio (o/e) 0.84, 90% interval 0.65 to 1.12. The synonymous counts are far from expectation, so gnomAD's model fits this gene poorly and the ratio says little. Missense variants: 576 observed, 573.12 expected, observed/expected ratio (o/e) 1, 90% interval 0.94 to 1.08. Synonymous variants: 281 observed, 229.69 expected, observed/expected ratio (o/e) 1.22, 90% interval 1.11 to 1.35.
Homologues: Orthologues: chimpanzee PANK2 (99% identical), macaque PANK2 (96% identical), pig PANK2 (95% identical), rabbit PANK2 (93% identical), dog PANK2 (92% identical), mouse Pank2 (91% identical), rat Pank2 (91% identical), tropical clawed frog pank2 (72% identical), zebrafish pank2 (67% identical), Drosophila melanogaster fbl (52% identical). Paralogues in human: PANK1 (68% identical), PANK3 (66% identical), PANK4 (30% identical).
Diseases named in the same sentence as PANK2 in open-access papers:
PANK2 is named in the same sentence as 73 diseases in open-access papers, as found by Europe PMC text mining. Sharing a sentence is not in itself a finding about the gene and the disease. The quoted sentences say what the papers report.
pantothenate kinase-associated neurodegeneration (46 papers, 2010 to 2025). "Pantothenate kinase-associated neurodegeneration (PKAN, OMIM#234200, formerly known as Hallervorden–Spatz syndrome), an autosomal recessive disease caused by mutations in the PANK2, is classified into two subtypes, namely, classic and atypical phenotype." (PMID 32928263, 2020). "Neurodegeneration with brain iron accumulation (NBIA), previously known as Hallervorden-Spatz syndrome, has been reported in recent years to be associated with PANK2 disease-causing genes, located at 20 p12." (PMID 29642163, 2018). "NBIA Type 1, panthotenate kinase associated neurodegeneration (PKAN), formerly called Hallervorden-Spatz disease, was discovered to be caused by the PANK2 gene." (PMID 23316402, 2012). "We report a case of a 13-year-old girl with Hallervorden-Spatz disease (HSD) or pantothenate kinase-2 associated neurodegeneration (PKAN)." (PMID 21042441, 2010). "Perhaps the best described disease associated with reduced cellular CoA-SH levels is pantothenate kinase-associated neurodegeneration (PKAN), also known as Hallervorden–Spatz disease, an autosomal recessive inherited disease caused by a mutation in the PANK2 gene." (PMID 33260564, 2020). "Background/Objectives: The most prevalent form of neurodegeneration with brain iron accumulation (NBIA) is pantothenate kinase-associated neurodegeneration (PKAN), caused by mutations in the PANK2 gene." (PMID 41009954, 2025). "The core syndrome among NBIA disorders is pantothenate kinase-associated neurodegeneration (PKAN), an autosomal recessive disorder caused by mutations in the PANK2 gene." (PMID 40113937, 2025). "Pantothenate kinase-associated neurodegeneration (PKAN) is a rare autosomal recessive hereditary neurodegenerative disorder, usually caused by mutations in the pantothenate kinase 2 (PANK2) gene." (PMID 39479227, 2024). "Among NBIA disorders, the most frequent subtype is pantothenate kinase-associated neurodegeneration (PKAN) caused by pathologic variants in the PANK2 gene codifying the enzyme pantothenate kinase 2 (PANK2)." (PMID 37895830, 2023). "Variation in the Pantothenate Kinase 2 (PANK2) gene, located on chromosome 20, has been previously associated with pantothenate kinase-associated neurodegeneration (PKAN), the most common subtype of NBIA44." (PMID 37024536, 2023). "Pantothenate kinase-associated neurodegeneration (PKAN) is an autosomal recessive disease caused by pathogenic variants in the pantothenate-kinase 2 gene (PANK2)." (PMID 37046296, 2023). "This study reveals altered carboxylate metabolism in erythrocytes of patients suffering from pantothenate kinase-associated neurodegeneration (PKAN) and describes the molecular effects of PANK2 point mutants on expression/stability and activity of the enzyme." (PMID 35204826, 2022). "Pantothenate kinase-associated neurodegeneration (PKAN) is a rare hereditary disease (prevalence of 1–2/1,000,000) with progressive neurodegeneration caused by mutations in the pantothenate kinase 2 gene (PANK2)." (PMID 35204826, 2022). "The importance of PanKs in human health was further highlighted by the discovery that mutations in the PANK2 gene are associated with pantothenate kinase-associated neurodegeneration (PKAN)." (PMID 36613877, 2022). "The more relevant form of NBIA is pantothenate kinase-associated neurodegeneration (PKAN), caused by PANK2 gene mutations, resulting in dystonia, dementia, dysphagia, spasticity, rigidity, and tremor: typically, with onset during childhood." (PMID 35251368, 2022). "The clinical entity caused by PANK2 mutations is termed pantothenate kinase-associated neurodegeneration (PKAN)." (PMID 35945593, 2022). "Pantothenate kinase-associated neurodegeneration (PKAN) is a progressive neurodegenerative disease caused by mutations in the pantothenate kinase 2 (PANK2) gene and associated with iron deposition in basal ganglia." (PMID 35204826, 2022).
pantothenate kinase-associated neurodegeneration (continued). "Pantothenate kinase-associated neurodegeneration (PKAN) is caused by mutations in the gene encoding pantothenate kinase 2 (PANK2) which is a major genetic defect in NBIA." (PMID 35408967, 2022). "The most common form of NBIA that occurs in 35–50% of NBIA cases is pantothenate kinase-associated neurodegeneration (PKAN), which arises from mutations in pantothenate kinase 2 (PANK2)." (PMID 34769423, 2021). "Pantothenate kinase-associated neurodegeneration (PKAN) is a rare disorder associated with brain iron accumulation caused by a recessive mutation in pantothenate kinase 2 gene (PANK2)." (PMID 34040814, 2021). "Mutations in the pantothenate kinase 2 gene (PANK2) are the cause of pantothenate kinase-associated neurodegeneration (PKAN), the most common form of neurodegeneration with brain iron accumulation." (PMID 33396642, 2020). "Biallelic mutations in PANK2 cause neurodegeneration with brain iron accumulation-1 also known as pantothenate kinase-associated neurodegeneration (PKAN), and previously known as Hallervorden-Spatz disease." (PMID 33488508, 2020). "Pantothenate kinase-associated neurodegeneration (PKAN) is an autosomal recessive disorder caused by mutation in the PANK2 gene." (PMID 29213449, 2016). "This led to introduction of the terms neurodegeneration with brain iron accumulation (NBIA) and pantothenate kinase-associated neurodegeneration (PKAN) to denote patients with suspected or proven mutation in the PANK2 gene." (PMID 29213449, 2016). "The first subtype of the Hallervorden-Spatz syndrome, identified by the mutation in the PANK2 gene and specific radiological and clinical findings, was denominated pantothenate kinase-associated neurodegeneration or PKAN." (PMID 29213449, 2016). "It includes pantothenate kinase-associated neurodegeneration (PKAN), which is a rare autosomal recessive disorder caused by the mutation of pantothenate kinase 2-gene (PANK2)." (PMID 30363610, 2015). "Pantothenate Kinase-Associated Neurodegeneration (PKAN) is a form of Neurodegeneration with Brain Iron Accumulation (NBIA) associated with mutations in the pantothenate kinase 2 gene (PANK2)." (PMID 25915509, 2015). "CoA deficiency is associated with severe human diseases, such as Pantothenate Kinase-Associated Neurodegeneration (PKAN) and CoASY protein-associated neurodegeneration (CoPAN), which are linked to genetic mutations in Pantothenate Kinase 2 (PANK2) and CoA Synthase (CoASY)." (PMID 39985665, 2025). "Pantothenate kinase-associated neurodegeneration (PKAN) is a rare autosomal recessive genetic disorder of PANK2, which enables mitochondrial synthesis of coenzyme A. Its loss causes neurodegeneration with iron accumulation primarily in motor-related brain areas." (PMID 37653408, 2023). "The gene for autosomal recessive neurodegeneration with brain iron accumulation type 1 (NBIA/DYT-PANK2, formerly known as Hallervorden–Spatz syndrome) has been identified as pantothenate kinase (PANK2)." (PMID 35207493, 2022). "A rare, life-threatening neurological disorder known as pantothenate kinase-associated neurodegeneration (PKAN) arises from mutations in the human PANK2 gene leading to a prominent extrapyramidal movement disorder and a characteristic deposition of iron in the basal ganglia." (PMID 35197056, 2022). "Altered CoA metabolism results in severe conditions such as pantothenate kinase-associated neurodegeneration (PKAN) in which a reduction of the activity of pantothenate kinase isoform 2 (PANK2) present in CoA biosynthesis in the brain consequently lowers the level of CoA in this organ." (PMID 34019583, 2021). "Furthermore, one patient in Group B had a PANK2 mutation, which is known to cause Hallervorden-Spatz Syndrome, or pantothenate kinase-associated neurodegeneration (PKAN)." (PMID 33209548, 2020).
pantothenate kinase-associated neurodegeneration (continued). "We appreciate Prof. Bing Zhou from Department of Biological Sciences and Biotechnology Tsinghua University, for the promoting of this study, who is the first author who identified the PANK2 defect in Hallervorden-Spatz syndrome in 2001." (PMID 32928263, 2020). "The father was carrying a heterozygous mutation c.1441C > T (p.Arg481Ter) in pantothenate kinase 2 (PANK2) (Hallervorden-Spatz syndrome), transmitted to the daughter." (PMID 32948218, 2020). "PANK2-specific NBIA, referred to as pantothenate kinase-associated neurodegeneration (PKAN) was formally called Hallervorden–Spatz syndrome before the name was changed to divert any association with the unethical euthanization of mentally ill patients during World War II by Dr. Hallervorden." (PMID 23531702, 2013). "The recognition that mutations of the pantothenate kinase 2 (PANK2) gene are the commonest cause of NBIA, also known as pantothenate kinase-associated neurodegeneration (PKAN), NBIA type 1 or HSS, has significantly advanced our understanding of this disorder." (PMID 22416811, 2013).
Dystonia (28 papers, 2013 to 2025). An abnormally increased muscular tone that causes fixed abnormal postures. "Putaminal and pallidal hypometabolism were present, alone or in combination, in all groups except PANK2, pointing towards common underlying primary and secondary pathophysiological mechanisms in dystonia." (PMID 36445406, 2023). "For instance, dystonia in early childhood can be caused by an autosomal recessive mutation in the pantothenate kinase 2 (PANK2) gene." (PMID 29910763, 2018). "Secondary dystonia was further subdivided into static lesions (such as extreme prematurity, vascular event, or hypoxic ischaemic encephalopathy), and progressive dystonias associated with neurodegenerative conditions such as PANK-2 deficiency." (PMID 27137203, 2016). "The patient, initially suspected of idiopathic isolated dystonia, finally presented with pantothenate kinase 2-associated neurodegeneration phenotype and was a carrier of two PANK2 mutations." (PMID 26087139, 2015). "She developed dystonia at the age of 7 and she was diagnosed as a carrier of the same PANK2 mutations." (PMID 26087139, 2015). "The analysis of oscillatory behavior across all frequency bands revealed that PANK2 and AOPEP neurons oscillate less (≤ 59.3%) than neurons of remaining dystonia‐causing genes." (PMID 39887724, 2025). "Cerebellar hypometabolism occurred in HPRT1, PANK2, CP-Kernicterus and CP-Preterm, four groups with severe baseline dystonia based on BFMDRS-M scoring." (PMID 36445406, 2023). "A study of 6 individuals with PANK2 mutation-positive PKAN showed a major and sustained improvement in painful spasms, dystonia, and ambulation." (PMID 33488508, 2020). "We demonstrate that GPi and GPe firing rates and patterns correlate with dystonia aetiology and phenotype, providing further evidence of differences in the pathophysiology of primary versus secondary dystonia, including PANK2-NBIA." (PMID 26848170, 2016). "Our findings indicate that pallidal neurones in PANK2-NBIA behave quite differently from those in patients with dystonia of various other aetiologies, indicating a different pathophysiology of PKAN versus other dystonias." (PMID 26848170, 2016). "A deleterious homozygous four-nucleotide deletion causing frameshift deletion in PANK2 gene (c.1426_1429delATGA, p.M476 fs) was identified in an 8 years old girl with dystonia, bone fracture, muscle rigidity, abnormal movement, lack of coordination and chorea." (PMID 28821231, 2017). "Furthermore, the striking differences in pallidal firing for PANK2-NBIA compared with other dystonia patients, alongside the FDG-PET-CT imaging patterns, could warrant the exploration of alternative or additional neuromodulation targets in this group, such as the subthalamic nucleus." (PMID 26848170, 2016). "Notably, we demonstrated that dystonia genes sharing a common molecular pathway, such as PLA2G6 and PANK2, can manifest opposite neural behaviors in the globus pallidus." (PMID 39887724, 2025). "The patient’s -249C>A substitution-negative sister who is PANK2 gene mutation carrier presented NBIA1 phenotype similar to the patient 4, whereas his -249C>A substitution positive father has not developed dystonia until the age of 52." (PMID 26087139, 2015). "The clinical phenotype of the cases with PANK2 and PLA2G6 is remarkably similar in the initial stages of the two diseases when it would be very difficult to differentiate the two as both have developmental delay, spasticity and dystonia." (PMID 22416811, 2013).
Parkinsonism (16 papers, 2009 to 2025). Characteristic neurologic anomaly resulting from degeneration of dopamine-generating cells in the substantia nigra, a region of the midbrain, characterized clinically by shaking, rigidity, slowness of movement and difficulty with walking and gait. "In Drosophila, the homolog of human PANK2 is fumble (fbl) (encoding Fbl, Fumble or dPANK), and inhibiting Fbl activity also causes severe neurological defects and reproduces some of the Parkinsonism symptoms." (PMID 35504872, 2022). "It is also reasonable that dysfunction of DJ-1 causes Parkinsonism as dysfunction of genes involved in the CoA biosynthetic pathway (PANK2 and COASY) trigger neurodegeneration with Parkinsonism." (PMID 28993701, 2017). "Decreased Th protein levels were found in whole brain from Pank2 KO animals, but the mice show no signs of parkinsonism." (PMID 31660701, 2019).
neurodegeneration with brain iron accumulation (15 papers, 2012 to 2025). "PKAN, a rare autosomal recessive movement disorder caused by mutations in PANK2, belongs to a heterogeneous group of neurodegenerative diseases named neurodegeneration with brain iron accumulation (NBIA)." (PMID 27516453, 2016). "The 2 major types of neurodegeneration with brain iron accumulation (NBIA) are the pantothenate kinase type 2 (PANK2)-associated neurodegeneration (PKAN) and NBIA2 or infantile neuroaxonal dystrophy (INAD) due to mutations in the phospholipase A2, group VI (PLA2G6) gene." (PMID 20619503, 2012). "Mutations in PANK2 cause pantothenate kinase‐associated neurodegeneration (PKAN), a neurodegeneration with brain iron accumulation (NBIA) disorder." (PMID 31660701, 2019). "PANK2, COASY, PLA2G6, and other genes related to iron homeostasis have been reported to cause diseases related to abnormal iron accumulation, such as neurodegeneration with brain iron accumulation (NBIA) and infantile neuroaxonal dystrophy (INAD)." (PMID 32457446, 2020).
Neurodegeneration (11 papers, 2015 to 2025). Progressive loss of neural cells and tissue. "Pantothenate Kinase Associated Neurodegeneration (PKAN) is an autosomal recessive disorder with mutations in the pantothenate kinase 2 gene (PANK2), encoding an essential enzyme for Coenzyme A (CoA) biosynthesis." (PMID 26476142, 2016). "PKAN is a progressive neurodegenerative disorder that affects movement, balance, speech, vision, cognition, and behavior, and it arises from pathological variants in the PANK2 gene." (PMID 39609877, 2024). "Mutations in PPCS and PPCDC are associated with forms of dilated cardiomyopathy, while variants in PANK2 and COASY cause neurological disorders classified as Neurodegenerations with Brain Iron Accumulation (NBIA)." (PMID 39301217, 2024). "Neurodegeneration associated with pantothenate kinase 2 deficiency (PKAN, also named NBIA1, OMIM # 234200) is an autosomal recessive disease which belongs to the group of disorders named Neurodegeneration with Brain Iron Accumulation (NBIA)." (PMID 36678831, 2023). "Variants in PANK2 cause pantothenate kinase-associated neurodegeneration (PKAN) (OMIM: #234200), while mutations in COASY cause COASY Protein-Associated Neurodegeneration (CoPAN) (OMIM: #615643)." (PMID 39301217, 2024). "Mutations in PANK2 cause PKAN (Pantothenate Kinase-Associated Neurodegeneration, MIM 234200), which is the most frequent NBIA form (35–50% of NBIA patients), and deficiency of COASY leads to COPAN (COasy Protein-Associated Neurodegeneration, MIM 615643), which is an ultra-rare form of NBIA." (PMID 32326494, 2020).
acanthocytosis (7 papers, 2013 to 2022). "Furthermore, the clinical overlap described between PKAN and HARP syndrome (hypoprebetalipoproteinaemia, acanthocytosis, retinitis pigmentosa and pallidal degeneration), which both derive from mutations in PANK2, strongly links lipid production deficits in PANK2 mutants." (PMID 25870938, 2016). "It has not been investigated yet whether acanthocytosis in PKAN is associated with a specific subset of Pank2 mutations." (PMID 25915509, 2015).